RNU6-1203P (RNA, U6 small nuclear 1203, pseudogene)
Gene: Small nuclear RNA gene on chromosome 12 (48,081,319 to 48,081,428, forward strand). Ensembl gene ENSG00000222635.
Homologues: Orthologues: chimpanzee U6 (99% identical), macaque U6 (80% identical), mouse Gm22975 (70% identical), rat LOC120093301 (65% identical). Paralogues in human: RNU6-820P (81% identical), RNU6-589P (79% identical), RNU6-1152P (78% identical), RNU6-1158P (78% identical), RNU6-140P (78% identical), RNU6-211P (78% identical), RNU6-246P (78% identical), RNU6-41P (78% identical), RNU6-44P (78% identical), RNU6-536P (78% identical), RNU6-1060P (77% identical), RNU6-1122P (77% identical), and 1286 more.